EPPK1 (epiplakin 1)
Diseases named in the same sentence as EPPK1 in open-access papers (continued):
Sharing a sentence is not in itself a finding about the gene and the disease.
tumor (12 papers, 2021 to 2025). "Last, Eppk1 lack in CC model causing a phenotype of tumor growth restraint is also essential." (PMID 33827480, 2021). "Research indicates that METTL3 facilitates tumor progression by regulating genes such as Bcl-2, EPPK1, and ACIN1." (PMID 40572597, 2025). "RNA sequencing revealed that EPPK1 KO induced downregulation of 11 oncogenes, 75 anti-apoptosis, and 22 angiogenesis genes while upregulating 8 tumor suppressors and 12 anti-cell growth genes." (PMID 38594604, 2024). "By comparing EPPK1 mRNA expression levels between normal and tumor tissues from multiple cancer types in TCGA dataset, we made several noteworthy observations." (PMID 38594604, 2024). "In the HPA data, compared with normal tissues, Chk2-pT68, EPPK1 and p16INK4a were expressed at medium to high levels in tumor tissues, while the expression of ER-alpha, PR and Annexin 1 was significantly downregulated in EC tumors." (PMID 35337291, 2022). "Furthermore, we examined the mRNA expression of EPPK1 to assess its relationship with tumor development." (PMID 38594604, 2024). "EPPK1 overexpression increased tumour growth and JUP expression in nude mice." (PMID 37328487, 2023). "Finally, Eppk1 expression is positively correlated with tumor size in clinicopathological features of CC." (PMID 33827480, 2021). "Additionally, we observed that EPPK1 KO resulted in decreased invasion and proliferation, changes in proteins associated with EMT signaling, and differential expression of key oncogenic, angiogenic, apoptotic, tumor suppressor, and anti-cell growth genes." (PMID 38594604, 2024). "Besides, expression of Eppk1 was a positive correlation with tumor size in CC tissues." (PMID 33827480, 2021). "EPPK1 is part of the epidermal growth factor (EGF) signal and is found to promote the proliferation of tumor cells." (PMID 35505821, 2022). "For ADAMTS12, AEBP1, COL10A1, COL11A1, CXCL11, EPPK1, and WNT7B, their expression values were higher in tumor samples than in normal samples." (PMID 35505821, 2022). "The analyses revealed that the LCN2 gene and its isoform ENST00000277480.6 showed a positive correlation only with protein cluster 2 comprising EPPK1 and ECADHERIN (tumor group 1) and SLC1A5 and GCN5L2 (tumor group 6)." (PMID 36211450, 2022). "Corresponding m/z from collagen type I alpha 2 (COL1A2), cathepsin (CTSG), elongation factor 1-alpha 1 (EEF1A1), EH domain-containing protein 2 (EHD2), epiplakin 1 (EPPK1), prelamin-A/C (LMNA), and prolargin (PRELP) showed higher intensity distribution in HND in comparison to LND tumour areas." (PMID 40603632, 2024). "The results showed the mRNA level of Eppk1 linkes to HPV positive infection rate and tumor size (P < 0.05), but not with pathological grade and clinical stage." (PMID 33827480, 2021).
cancer (9 papers, 2017 to 2025). A tumor composed of atypical neoplastic, often pleomorphic cells that invade other tissues. "Based on our data indicating the association of EPPK1 with cancer development and EMT we conducted an analysis of cell growth and invasion following the KO of EPPK1." (PMID 38594604, 2024). "Our data suggest that EPPK1 is linked to smoking, epithelial to mesenchymal transition, and the regulation of cancer progression, indicating its potential as a therapeutic target for LUAD." (PMID 38594604, 2024). "To investigate the potential association of EPPK1 with OS across multiple cancers, we analyzed mRNA expression data from TCGA database." (PMID 38594604, 2024). "An effect on cell proliferation has previously been reported in cancer models showing that EPPK1 knockdown inhibits cell proliferation, a phenotype opposite to that observed in psoriatic epidermis." (PMID 40746860, 2025). "Our findings revealed a significant correlation between EPPK1 expression and poor prognosis in various cancers." (PMID 38594604, 2024). "We also investigated the expression of EPPK1 in multiple cancer types compared to that in normal tissues and its role in the survival of various cancers and early-stage LUAD." (PMID 38594604, 2024). "For PLEC and EPPK1, 19 datasets show increased expression in cancers, while only 8 datasets and 7 datasets demonstrate decreased expression of PLEC and EPPK1 in cancers, respectively." (PMID 29587367, 2018). "This study aimed to identify a probable crucial role for EPPK1 in cancer development." (PMID 38594604, 2024). "Therefore, our results suggest that EPPK1 plays a crucial role in the regulation of cancer development in LUAD through its effects on multiple signaling pathways and genes." (PMID 38594604, 2024). "Based on our findings indicating the critical role of EPPK1 in cancer development and its association with poor prognosis in LUAD and other cancers, we aimed to investigate whether the loss of EPPK1 function could impede cancer progression." (PMID 38594604, 2024). "While the exact role of EPPK1 remains unclear, our previous findings led us to hypothesize that EPPK1 plays a crucial role in cancer development." (PMID 38594604, 2024). "However, it significantly increases in severe pathological changes in cervical tissues, such as CINII-III and cancer, which would be like to the regeneration and development of injured tissues or the tumorigenesis and development of cancer with upregulation of Eppk1." (PMID 33827480, 2021). "Lastly, we demonstrated that EPPK1 plays a crucial role in the regulation of EMT and cancer development in LUAD by affecting multiple signaling pathways and genes." (PMID 38594604, 2024). "Firstly, we observed elevated expression of EPPK1 mRNA in LUAD (P < 0.01) and LUSC (P < 0.001) as well as in several other cancers, in comparison to that in normal tissues." (PMID 38594604, 2024). "Based on our accumulated evidence indicating the involvement of EPPK1 in cancer development, EMT, cell proliferation, and cell invasion, we employed RNA sequencing to examine the expression levels of WT and KO EPPK1." (PMID 38594604, 2024). "Further, we used CRISPR-Cas9 to knock out (KO) EPPK1 in LUAD cell lines and observed how the cancer cells were altered functionally and genetically." (PMID 38594604, 2024). "Therefore, our results indicate that FCGR2A, PDE3A, and EPPK1 are the main target genes for MYBL2 and may function as novel cancer biomarkers." (PMID 35664780, 2022).
EPPK1 also shares sentences with these, for which no sentence is quoted: bladder urothelial carcinoma (2 papers); esophageal squamous cell carcinoma (2); bladder cancer (1); brain disorder (1); infection (1); non-small cell lung carcinoma (1); Obesity (1).